KYAT3 (kynurenine aminotransferase 3)
Description:
Catalyzes the irreversible transamination of the L-tryptophan metabolite L-kynurenine to form kynurenic acid (KA), an intermediate in the tryptophan catabolic pathway which is also a broad spectrum antagonist of the three ionotropic excitatory amino acid receptors among others. May catalyze the beta-elimination of S-conjugates and Se-conjugates of L-(seleno)cysteine, resulting in the cleavage of the C-S or C-Se bond. Has transaminase activity towards L-kynurenine, tryptophan, phenylalanine, serine, cysteine, methionine, histidine, glutamine and asparagine with glyoxylate as an amino group acceptor (in vitro). Has lower activity with 2-oxoglutarate as amino group acceptor (in vitro).
Synonyms: KATIII; CCBL2; KAT3; RBM1; RP11-82K18.3
Tractability: PROTAC: ubiquitination databases record sites on it; a small molecule that binds it is known.
Target class: Enzyme
Gene: Protein-coding gene on chromosome 1 (88,935,773 to 88,992,953, reverse strand). Ensembl gene ENSG00000137944.
Subcellular location (Human Protein Atlas): Cytosol; Cytokinetic bridge; Nucleoli
Pathways (Reactome):
Metabolism: Tryptophan catabolism
Gene Ontology:
Molecular function: RNA binding; cysteine-S-conjugate beta-lyase activity; kynurenine-glyoxylate transaminase activity; kynurenine-oxoglutarate transaminase activity; pyridoxal phosphate binding
Cellular component: mitochondrion
Genetic constraint (gnomAD): Loss-of-function variants: 20 observed, 25.24 expected, observed/expected ratio (o/e) 0.79, 90% interval 0.56 to 1.15. The synonymous counts are far from expectation, so gnomAD's model fits this gene poorly and the ratio says little. Missense variants: 233 observed, 266.53 expected, observed/expected ratio (o/e) 0.87, 90% interval 0.79 to 0.97. Synonymous variants: 67 observed, 91.77 expected, observed/expected ratio (o/e) 0.73, 90% interval 0.6 to 0.89.
Homologues: Orthologues: chimpanzee KYAT3 (99% identical), macaque KYAT3 (98% identical), dog KYAT3 (91% identical), rabbit KYAT3 (87% identical), guinea pig KYAT3 (85% identical), pig KYAT3 (84% identical), mouse Kyat3 (83% identical), rat Kyat3 (82% identical), tropical clawed frog kyat3 (70% identical), zebrafish kyat3.1 (62% identical), zebrafish kyat3.2 (62% identical), Drosophila melanogaster Kyat (50% identical), and 4 more. Paralogues in human: KYAT1 (47% identical), GPT (17% identical), GPT2 (17% identical), ACCS (16% identical), ACCSL (16% identical), TAT (16% identical), AADAT (14% identical).
Diseases named in the same sentence as KYAT3 in open-access papers:
KYAT3 is named in the same sentence as 22 diseases in open-access papers, as found by Europe PMC text mining. Sharing a sentence is not in itself a finding about the gene and the disease.
KYAT3 shares sentences with these, for which no sentence is quoted: cancer (3 papers); tumor (3); Alzheimer disease (1); Breast Invasive Carcinoma (1); cholangiocarcinoma (1); COVID-19 (1); depression (1); glioma (1); head and neck cancer (1); Huntington disease (1); Hyperoxaluria (1); infiltrating ductal carcinoma (1); leprosy (1); liver cancer (1); lobular carcinomas (1); melanoma (1); neurodegenerative disease (1); neurological diseases (1); ovarian carcinoma (1); renal carcinoma (1); schizophrenia (1); uterine corpus endometrial carcinoma (1).